GACAT2 (gastric cancer associated transcript 2)
Synonyms: HMlincRNA717; MTCL1-AS1; MTCL1AS1
Gene: Long non-coding RNA gene on chromosome 18 (8,695,856 to 8,707,721, reverse strand). Ensembl gene ENSG00000265962.
Diseases named in the same sentence as GACAT2 in open-access papers:
GACAT2 is named in the same sentence as 6 diseases in open-access papers, as found by Europe PMC text mining. Sharing a sentence is not in itself a finding about the gene and the disease. The quoted sentences say what the papers report.
gastric cancer (6 papers, 2020 to 2023). A primary or metastatic malignant neoplasm involving the stomach. "Moreover, HULC, H19, HOTAIR and GACAT2 (for “gastric cancer-associated transcript 2”) were found to be significantly increased in the plasma of gastric cancer (GC) patients compared to healthy individuals." (PMID 35729321, 2022). "HULC, H19, HOTAIR, and GACAT2 (for “gastric cancer-associated transcript 2”) were found to be significantly increased in the plasma of gastric cancer (GC) patients compared to healthy individuals." (PMID 37190024, 2023). "Given that GACAT2 has been previously developed as a potential biomarker in the diagnosis of gastric cancer, we tentatively investigated the clinical significance of GACAT2 expression in gingival tissues for root cementum damage." (PMID 35296649, 2022). "In addition, LINC01269 is related to the prognosis of liver cancer, while GACAT2 influences the prognosis of gastric cancer." (PMID 36118853, 2022). "This implies that diagnosis based on the quantification of plasmatic levels of H19 or GACAT2 may potentially result in a significant number of false-positive results when testing for gastric cancer." (PMID 35729321, 2022). "The levels of plasma gastric cancer associated transcript 2 (GACAT2) were higher in patients with GC than in non-GC controls, as well as in preoperative than that in postoperative samples." (PMID 33036473, 2020).
breast carcinoma (1 paper, 2022). "In contrast, the coefficients of AC115837.2, LINC01269, AL645608.7, and GACAT2 were positive, indicating that they are high-risk lncRNAs and have a promoting effect on breast cancer." (PMID 36118853, 2022).
periodontitis (1 paper, 2022). An acute or chronic inflammatory process that affects the tissues that surround and support the teeth. "Here, the clinical significance of GACAT2 in periodontitis was indirectly demonstrated by the lower expression of GACAT2 in gingival tissues from teeth with periodontitis than in those from healthy tissues." (PMID 35296649, 2022). "As expected, lower GACAT2 expression was observed in gingival tissues of teeth with periodontitis with damaged cementum than in those from healthy teeth." (PMID 35296649, 2022).
cancer (1 paper, 2021). A tumor composed of atypical neoplastic, often pleomorphic cells that invade other tissues. "Therefore, they believed that plasma GACAT2 could be used as a tumor marker for the screening and prognosis prediction of cancer patients." (PMID 33995377, 2021).
GACAT2 also shares sentences with these, for which no sentence is quoted: liver cancer (1 paper); tumor (1).